SPINK7 (serine peptidase inhibitor Kazal type 7)
Description:
Probable serine protease inhibitor.
Synonyms: ECG2; ECRG2
Tractability: Antibody: UniProt places it where antibodies can reach, with high confidence; UniProt predicts a signal peptide or a membrane-spanning region; its Gene Ontology location is reachable by antibodies, with medium confidence.
Gene: Protein-coding gene on chromosome 5 (148,312,419 to 148,315,922, forward strand). Ensembl gene ENSG00000145879.
Subcellular location: Secreted
Gene Ontology:
Molecular function: protein binding; serine-type endopeptidase inhibitor activity
Biological process: inflammatory response; negative regulation of proteolysis
Cellular component: extracellular region
Genetic constraint (gnomAD): Loss-of-function variants: 3 observed, 5.48 expected, observed/expected ratio (o/e) 0.55, 90% interval 0.25 to 1.39. That is too few expected variants to judge how well the gene tolerates losing a copy. Missense variants: 57 observed, 54.74 expected, observed/expected ratio (o/e) 1.04, 90% interval 0.84 to 1.3. Synonymous variants: 19 observed, 19.96 expected, observed/expected ratio (o/e) 0.95, 90% interval 0.66 to 1.4.
Homologues: Orthologues: chimpanzee SPINK7 (100% identical), macaque SPINK7 (96% identical), dog SPINK7 (84% identical), pig SPINK7 (81% identical), rabbit SPINK7 (80% identical), rat Spink7 (68% identical), mouse Spink7 (67% identical), guinea pig SPINK7 (66% identical). Paralogues in human: SPINK14 (38% identical), SPINK9 (38% identical), SPINK2 (32% identical), SPINK8 (27% identical), SPINK13 (26% identical).
Diseases named in the same sentence as SPINK7 in open-access papers:
SPINK7 is named in the same sentence as 27 diseases in open-access papers, as found by Europe PMC text mining. Sharing a sentence is not in itself a finding about the gene and the disease. The quoted sentences say what the papers report.
esophageal cancer (8 papers, 2014 to 2025). A primary or metastatic malignant neoplasm involving the esophagus. "In the northern Indian population, the SPINK7 TCA3/TCA4 genotype is associated with the risk of esophageal cancer." (PMID 35223512, 2022). "SPINK7 was initially identified as tumour suppressor of oesophageal cancer that suppresses tumour cell migration and invasion through inhibiting uPA/uPAR signalling." (PMID 40147022, 2025). "It is reported that SPINK7 is a novel candidate of the tumor suppressor gene identified from human esophagus and plays an important role in the carcinogenesis of esophageal cancer." (PMID 29301256, 2018). "SPINK7 is consistently expressed at high levels in the human oesophageal epithelium, and studies have demonstrated its substantial contribution to the pathogenesis of oesophageal cancer and eosinophilic oesophagitis." (PMID 40147022, 2025). "Many studies suggested that SPINK7 may function as a tumor suppressor gene regulating the protease cascades during carcinogenesis and invasion of esophageal cancer." (PMID 29301256, 2018). "Recent reports have indicated that SPINK7 is a serine protease inhibitor having ability to inhibit uPA and MMP2 activities, which plays important roles in tumorigenesis and development of oesophagus cancer." (PMID 40147022, 2025). "Esophageal Cancer-Related Gene 2 (ECRG2), also known as Serine Peptidase Inhibitor Kazal type 7 (SPINK7), is a putative tumor suppressor gene that was originally discovered by studies attempting to identify genes that were involved in human esophageal cancer." (PMID 38892042, 2024).
gastric cancer (5 papers, 2019 to 2025). A primary or metastatic malignant neoplasm involving the stomach. "A previous study on salivary exRNA biomarkers showed that three mRNAs (SPINK7, PPL, and SEMA4B mRNAs) and two miRNAs (miR140-5p and miR301a) were significantly down-regulated in gastric cancer patients compared with healthy individuals in a Korean population." (PMID 40429589, 2025). "This study showed that three mRNAs (SPINK7, PPL, and SEMA4B) and two miRNAs (miR140-5p and miR301a) were significantly downregulated in gastric cancer patients." (PMID 40429589, 2025). "For example, in a study, 5 exRNAs, including 3 mRNAs (SPINK7, PPL, and SEMA4B) and 2 microRNAs (MIR140-5p and MIR301a), showed downregulation in gastric cancer (GC)." (PMID 35948986, 2022). "SPINK7 is highly expressed in chromophobe RCC, but the SPINK7 mRNA level is downregulated in the saliva of patients with gastric cancer." (PMID 35223512, 2022).
eosinophilic esophagitis (4 papers, 2024 to 2026). Eosinophilic esophagitis (EoE) is a chronic, allergic disease of the esophagus characterized clinically by symptoms of esophageal dysfunction (including vomiting, dysphagia, feeding disorders, food impaction and abdominal pain) which persist after treatment with proton pump inhibitors (PPIs). "The protease inhibitor activity of ECRG2/SPINK7 protein has also been linked to an allergic condition of the esophagus in humans known as eosinophilic esophagitis (EoE)." (PMID 38892042, 2024). "SPINK7 deficiency results in the unleashing of proteolytic activities and proinflammatory innate responses in oesophageal epithelium through regulating uPA and kallikrein 5 (KLK5), which makes significant contributions to eosinophilic esophagitis (EoE) pathogenesis." (PMID 40147022, 2025). "SPINK 7, also known as ECRG2, is being recognised as an important regulator of oesophageal epithelial barrier integrity and immunological homeostasis in eosinophilic esophagitis (EoE)." (PMID 40872585, 2025).
colitis (3 papers, 2023 to 2025). Inflammation of the colon. "Spink7, mainly derived from neutrophils, showed a protective role in the murine colitis model, while Spink7-deficient mice preformed remarkably susceptible to experimental colitis." (PMID 37063924, 2023). "What's more, our recent work indicates that Spink7 derived from neutrophils exerts a protective effect by inhibiting multiple proinflammatory cytokines and chemokines in experimental murine colitis models." (PMID 40147022, 2025). "Our previous study revealed that Spink7 derived from neutrophils exerts a protective role by controlling chemokines/cytokines production in experimental murine colitis." (PMID 40147022, 2025). "Our previous work shows that Spink7 exerts an important protective role in experimental colitis." (PMID 40147022, 2025). "They found that ECRG2/SPINK7 was significantly elevated in dextran sodium sulfate (DDS)-induced colitis in mice and, interestingly, cells with elevated ECRG2/SPINK7 expression in colitis tissues were mainly the neutrophils." (PMID 38892042, 2024).
oral squamous cell carcinoma (3 papers, 2020 to 2024).
cervical squamous cell carcinoma (2 papers, 2020 to 2024). A squamous cell carcinoma arising from the cervical epithelium. "In addition, a reduction of ECRG2/SPINK7 was also found in several other human malignancies, i.e., head and neck squamous cell cancer, cervical squamous cell carcinoma, and endocervical adenocarcinoma, which was associated with reduced disease-free survival in patients." (PMID 38892042, 2024).
Fungal Infection (2 papers, 2021 to 2025). "In silkworm (Bombyx mori), SPINK7 is exclusively expressed in haemocytes, and research has shown its important role in immune defence against fungal infections." (PMID 40147022, 2025).
asthma (1 paper, 2025). "For asthma and COPD, one SNP rs11168048 located at 5q32 (harboring HTR4, FBXO38, and SPINK7) and two SNPs rs2122190 located at 5q23.1 (harboring PRR16) and rs6860087 located at 5q32 (harboring HTR4) were identified." (PMID 41295252, 2025).
dysplasia (1 paper, 2021). A usually neoplastic transformation of the cell, associated with altered architectural tissue patterns. "We found that SPINK7(green signal) and HER2 (red signal) had significantly decreased in the less invasive OSCC group compared with dysplasia and highly invasive OSCC groups (p < 0.05)." (PMID 33767253, 2021).
inflammatory skin disease (1 paper, 2022). Inflammatory skin disorders covers a broad category that includes many conditions ranging in severity, from mild itching to grave medical health complications These disorders are common in people of all ages and races. "Another study showed that SPINK7 played an important role in skin homeostasis and inflammatory skin diseases." (PMID 35846149, 2022).
pancreatic cancer (1 paper, 2025). "Our data indicate that SPINK7 is highly expressed in pancreatic cancer tissues and correlates with poor prognosis." (PMID 41008826, 2025).
tumor (12 papers, 2014 to 2025). "SPINK7 suppresses tumor development by inducing apoptosis and binding directly to the urokinase-type plasminogen activator (uPA)." (PMID 40872585, 2025). "Variations in SPINK7 expression were shown to be related to tumor development and aggressiveness, indicating a role in OSCC pathogenesis." (PMID 40872585, 2025). "QRT-PCR showed that the expression of FAM83 and DKK1 was significantly upregulated in tumor samples, while SPINK7 was downregulated." (PMID 38518012, 2024). "The results showed that the methylation levels of FAM83E, CD79A, and SPINK7 were reduced in tumor tissues with poor clinical staging, while DKK1 was elevated in tumor tissues." (PMID 38518012, 2024). "Since its discovery, multiple lines of evidence have demonstrated that ECRG2/SPINK7 is an important tumor suppressor, which is instrumental in numerous cellular phenotypes." (PMID 38892042, 2024). "It has been reported that SPINK7 inhibits tumor cell growth, promotes cell apoptosis, and inhibits cancer cell migration, invasion and metastasis in vitro." (PMID 33767253, 2021). "SPINK7 is a potential molecular target in tumor biotherapy strategies." (PMID 35223512, 2022). "Additionally, SPINK7 has been shown to function as a tumor suppressor in the DNA damage response, suggesting it may play wider protective roles in epithelial tissue biology." (PMID 40872585, 2025). "The SPINK7 gene, also called oesophageal cancer-related gene 2, is hypothesised to operate as a tumor-suppressor gene, controlling protease cascades in carcinogenesis and oesophageal carcinoma invasion by regulating migration via the urokinase-type plasmin activator/plasmin MAPK pathway." (PMID 40872585, 2025). "ECRG2/SPINK7 inhibits cancer cell migration and invasion and also suppresses tumor metastasis in animals." (PMID 38892042, 2024). "Results showed that IFI27, KIF20A, KLK10 and TOP2A were significantly upregulated in tumor cells relative to normal cells, whereas SPINK7 showed no differential expression." (PMID 41008826, 2025). "Reduced or absent ECRG2/SPINK expression occurs in various human malignancies; cancer patients with low ECRG2/SPINK7 expression in their tumor tissues exhibit shorter disease-free survival." (PMID 38892042, 2024).
cancer (9 papers, 2016 to 2025). A tumor composed of atypical neoplastic, often pleomorphic cells that invade other tissues. "The overexpression of ECRG2/SPINK7 causes cancer cell death via multiple mechanisms." (PMID 38892042, 2024). "Thus, evidence indicates that defective ECRG2/SPINK7 (due to reduced expression or mutations) may be one of the important factors in human cancer development and acquisition of anticancer drug resistance." (PMID 38892042, 2024). "SPINK7 loss increases this interaction, stimulating the Src/MAPK pathway and promoting cancer cell motility and invasion." (PMID 40872585, 2025). "Among them, 8 of 12 hub genes (EPHX3, SPINK7, FCRLA, MASP1, ZNF541, CD5, BEST2, ZAP70) seemed to be cancer-promoting genes as they were downregulated in the high-risk group." (PMID 35846149, 2022). "SPINK7 binds to uPA, which reduces proteolysis and slows cancer cell proliferation." (PMID 40872585, 2025). "SPINK7 can bind to uPA with molecular weights of 55 and 33 kDa, reducing the proteolysis of the plasmin substrate d-v-ph-lys-p-nitroaniline and inhibiting the growth of cancer cells by downregulating uPA/plasmin activity." (PMID 35223512, 2022). "SPINK7 deletion may lead to chromosome instability and aneuploidy in human cancer." (PMID 35223512, 2022). "All lines of evidence signify the importance of ECRG2/SPINK7 in human tumorigenesis and suggest that restoring ECRG2/SPINK7 function in cancer cells may be an attractive therapeutic strategy." (PMID 38892042, 2024).
infection (1 paper, 2021). The state of being infected such as from the introduction of a foreign agent such as serum, vaccine, antigenic substance or organism. "Quantitative real-time PCR analyses revealed that SPINK7 was exclusively expressed in hemocytes and was upregulated after infection with two fungi, Saccharomyces cerevisiae and Candida albicans." (PMID 34603317, 2021). "The qPCR was also used to investigate SPINK7 expression after infection with two kinds of fungi: S. cerevisiae and C. albicans." (PMID 34603317, 2021). "BmSPI65 (SPINK7) and BmSPI66 (SPINK8) showed significant upregulation in the hemolymph after infection with Gram-negative Escherichia coli and Gram-positive Staphylococcus aureus." (PMID 34603317, 2021).
SPINK7 also shares sentences with these, for which no sentence is quoted: endocervical adenocarcinoma (2 papers); esophageal squamous cell carcinoma (2); lung carcinoma (2); cervical carcinoma (1); colon cancer (1); gastric adenocarcinoma (1); head and neck squamous cell carcinoma (1); hepatocellular carcinoma (1); melanoma (1); pancreatic adenocarcinoma (1); prostate carcinoma (1); skin carcinoma (1); ulcers (1).